SFRP5 (secreted frizzled related protein 5)
Diseases named in the same sentence as SFRP5 in open-access papers (continued):
Sharing a sentence is not in itself a finding about the gene and the disease.
gastric cancer (8 papers, 2008 to 2024). A primary or metastatic malignant neoplasm involving the stomach. "SFRP5 is known to be associated with hepatocellular carcinoma and gastric cancer." (PMID 39202484, 2024). "Therefore, Wnt5a overproduction and SFRP5 deficiency in gastric mucosa may together play an important role in gastric cancer initiation." (PMID 24416340, 2014). "Overexpression of Wnt5a and downregulation of SFRP5, a Wnt5a antagonist, were both observed in gastric cancers recently." (PMID 24416340, 2014). "Our initial finding showed that SFRP5 expression is significantly downregulated in gastric cancer, while the subsequent quantitative real-time PCR analysis revealed that MMP-2, MMP-7, MMP-9 and MT1-MMP are all upregulated in it." (PMID 19586554, 2009). "The aim of this study is to determine the expression status of SFRP5 in gastric cancer and explore the correlation between both the expression of SFRP5 and that of these MMPs in this cancer." (PMID 19586554, 2009). "Expression of SFRP5 mRNA was determined by real-time reverse-transcription PCR in 32 gastric cancer specimens and corresponding matched normal tissue specimens." (PMID 19586554, 2009). "Taken together, these results suggest a strong link between the common SFRP5 downregulation and its methylation in gastric cancer." (PMID 19586554, 2009). "First, as a putative tumor suppressor gene, SFRP5 is downregulated in a series of human cancers, including gastric cancer; and in most cases, it can lead to aberrant activation of Wnt signal pathway." (PMID 19586554, 2009). "The results indicate there are frequent occurrences of downregualtion of SFRP5 expression in gastric cancer, primarily due to SFRP5 methylation." (PMID 19586554, 2009). "MSP analysis indicated a connection between the absence of SFRP5 and its methylation in all these five cell lines and 21 out of the 24 SFRP5-downregulated gastric cancer specimens, for there is a resumption of it with these cell lines demethylated by DAC." (PMID 19586554, 2009). "Taken together, all the lines of evidence suggest a prevalence of SFRP5 downregulation in gastric cancer, which is responsible for the upregulation of the expression of MMP-7 and MT1-MMP." (PMID 19586554, 2009). "SFRP5 expression was frequently downregulated in gastric cancer due to SFRP5 gene hypermethylation, which was hypothesized to lead to uncontrolled activation of Wnt5a signal pathways." (PMID 24416340, 2014). "The first line of evidence comes from the expression status of SFRP5 in primary gastric cancers." (PMID 19586554, 2009). "To further investigate the role of promoter methylation in the downregulation of SFRP5 expression in gastric cancer, we defined SFRP5 mRNA downregulation more than 10-fold as negative expression, and SFRP5 mRNA downregulation less than 10-fold or SFRP5 mRNA upregulation as positive expression." (PMID 19586554, 2009). "The detection reported SFRP5 methylation in 22 (69%) of the 32 gastric cancer specimens." (PMID 19586554, 2009). "SFRP5 expression and SFRP5 methylation in primary gastric cancer specimens." (PMID 19586554, 2009). "Such a finding that these MMPs are the targets of Wnt signaling led to our initial hypothesis: there may be a link between downregulation of SFRP5 and overexpression of these MMPs in gastric cancer." (PMID 19586554, 2009). "Previous data suggested that decreased SFRP5 gene level promoted the production of matrix metalloproteinase (MMP) and lead to the migration and metastasis of gastric cancer cells." (PMID 33573682, 2021). "The assumption of a link between downregulation of SFRP5 and upregulation of MMPS in gastric cancer is based on the following findings." (PMID 19586554, 2009). "SFRP5 expression was remarkably downregulated in 24 of 32 primary gastric cancer specimens, and even was not detectable in 5 of 8 gastric cancer cell lines." (PMID 19586554, 2009).
gastric cancer (continued). "As for the correlation between expression of SFRP5 and those of these MMPs, mRNA expression of these MMPs was examined when we compared gastric cancer specimens with negative SFRP5 expression to those with positive one." (PMID 19586554, 2009). "In human gastric cancer, EZH2 promotes the activation of Wnt/β-catenin signaling by down-regulating CXXC4 expression, and several other Wnt pathway antagonists, including NKD1, PRICKLE1, PPP2R2B, AXIN2 and SFRP5, were concordantly silenced by EZH2 in hepatocellular carcinomas." (PMID 27926488, 2017). "We previously showed that SFRP1, SFRP2 and SFRP5 are frequently inactivated in CRC and gastric cancer (GC), and that SFRPs suppress constitutive Wnt signalling when overexpressed in CRC and GC cells." (PMID 18283316, 2008). "The focus is then shifted onto the significant downregulation (>10-fold) of SFRP5, another member of SFRP family, in 75% of the total gastric cancer specimens, and no detectable expression of it in 5 out of the total 8 gastric cell lines tested." (PMID 19586554, 2009).
myocardial infarction (8 papers, 2017 to 2025). Gross necrosis of the myocardium, as a result of interruption of the blood supply to the area, as in coronary thrombosis. "The aim of our study was to explore the effects of Sfrp5 on hearts after myocardial infarction (MI) and to investigate the underlying mechanisms." (PMID 34568442, 2021). "This phenomenon suggests a potential role for SFRP5 in predicting or assessing cardiac function recovery throughout the clinical trajectory following myocardial infarction." (PMID 37957661, 2023). "For example, there is a downregulation of SFRP5 in cardiac tissue post-myocardial infarction (MI) in mice." (PMID 37504530, 2023). "In mice, Sfrp5 reduced myocardial infarction size and myocyte apoptosis in the heart after ischaemia/reperfusion injury." (PMID 28851362, 2017). "The knockout of Sfrp5 in mice led to an increased size of myocardial infarction, a higher myocyte apoptosis rate and enhanced mRNA levels of pro-inflammatory proteins in the ischaemic area." (PMID 28851362, 2017). "Furthermore, the role of SFRP5 in myocardial infarction of type 2 diabetic mice was observed in vivo." (PMID 35506262, 2022). "Furthermore, we and others have demonstrated that a blockade of Wnt ligands with extracellular Wnt inhibitors like WIF1 and SFRP5 also improves the healing process of myocardial infarction by modulating the inflammatory response." (PMID 36293109, 2022).
Glucose intolerance (7 papers, 2014 to 2024). Glucose intolerance (GI) can be defined as dysglycemia that comprises both prediabetes and diabetes. "In contrast, Sfrp5 deficiency led to severe glucose intolerance and further impaired insulin-stimulated phosphorylation of Akt in adipose tissue following high-fat feeding as compared to wild-type mice." (PMID 24465779, 2014). "A previous study demonstrated in their SFRP5-deficient mouse models that inducing severe macrophage infiltration could cause serious glucose intolerance, insulin resistance, as well as inflamed adipose tissue." (PMID 29789397, 2018). "Importantly, Sfrp5-deficiency in mice results in deterioration of high-calorie diet-induced glucose intolerance, hepatic steatosis and macrophage infiltration in adipose tissue." (PMID 24465779, 2014).
heart failure (7 papers, 2021 to 2025). Inability of the heart to pump blood at an adequate rate to meet tissue metabolic requirements. "Clinically, low SFRP5 (or high Wnt5a/SFRP5 ratio) is associated with worse outcomes in heart failure and acute MI." (PMID 41465371, 2025). "Multicenter cohort studies suggest that circulating SFRP5 is lowered and correlates with worsened prognosis in heart failure and T2D patients." (PMID 40427505, 2025). "Patients with heart failure demonstrated a significantly lower median SFRP5 concentration relative to patients with arrhythmias, with insignificant differences regarding WNT5a and STAT5A expressions between patients with different cardiac diseases." (PMID 41465371, 2025). "SFRP5 is a crucial predictor of heart failure prognosis, and lowered SFRP5 levels are corrected with vascular calcification and coronary atherosclerosis." (PMID 40427505, 2025). "The SFRP5 recombinant protein has a protective effect on isoproterenol-induced heart failure in mice." (PMID 35685732, 2022). "This study aims to explore the myocardial protective effect of secreted frizzled-related protein 5 (SFRP5) on mice with heart failure." (PMID 35685732, 2022). "Our results indicated that B-lines by lung ultrasound could be a promising marker to predict heart failure, such as secreted frizzled-related protein 5(SFRP5) and extracellular volume fraction by cardiovascular magnetic resonance." (PMID 35586654, 2022). "SFRP5 may be one of the therapeutic targets of heart failure." (PMID 35685732, 2022).
Hyperglycemia (6 papers, 2014 to 2024). An increased concentration of glucose in the blood. "Circulating SFRP5 expression during an oral glucose tolerance test was both rapidly and markedly reduced in response to hyperglycemia." (PMID 29789397, 2018). "It is worth mentioning that during HEC normal plasma glucose level is maintained, thus we may exclude the potential effect of hyperglycemia on circulating SFRP5 levels." (PMID 34184187, 2021). "Moreover, a previous study demonstrated that hyperglycemia achieved through oral glucose intake decreased circulating sFRP5 levels, suggesting that sFRP5 release is influenced by metabolic stress." (PMID 32429518, 2020).
Hypertension (6 papers, 2017 to 2026). The presence of chronic increased pressure in the systemic arterial system. "At baseline, obese children with hypertension had lower Sfrp5 and higher Wnt5a concentrations, whereas a reduction of BMI and blood pressure after 6 months resulted in increased Sfrp5 concentrations." (PMID 34371968, 2021). "In obese children with hypertension plasma SFRP5 was reduced, while lifestyle intervention did not only improve blood pressure and BMI but also increased plasma SFRP5." (PMID 28851362, 2017). "Accordingly, implementation of a lifestyle intervention program in obese children with hypertension resulted in a rapid decrease in Sfrp5 but no change in Wnt5a concentrations." (PMID 34371968, 2021).
lung carcinoma (6 papers, 2010 to 2022). "Limited information suggested that SFRP5 was low in pleura mesothelioma, and methylation of SFRP5 was associated with overall survival of lung cancer." (PMID 24899788, 2014).
liver disease (5 papers, 2008 to 2023). "Previous data additionally suggest regulation of the Wnt5a/SFRP5 system in liver disease including non-alcoholic fatty liver disease (NAFLD)." (PMID 36830849, 2023). "Nevertheless, patients with known liver disease as well as chronic alcohol abuse showed higher serum levels of SFRP5, but this only reached statistical significance for patients with liver disease (p = 0.005)." (PMID 36830849, 2023). "We now demonstrate higher levels of SFRP5 in critically ill patients with liver disease." (PMID 36830849, 2023). "In other ways, the expression of SFRP5 in adipose tissue of NAFLD patients it could be also increased by the liver disease itself given the intercommunication between both tissues." (PMID 36077270, 2022). "SFRP5 levels in patients with different liver disease statuses were investigated." (PMID 25120720, 2014). "Furthermore, SFRP5 levels differentially decreased in patients with HBV-associated diseases, in a manner which was dependent on liver disease status." (PMID 25120720, 2014). "We have identified eight potential FZD activating events, each occurring in a significant proportion of HCCs (⩾20%) – that is, upregulation of FZD3/6/7 and WNT3/4/5A, and repression of sFRP1/sFRP5 – which accumulate with severity of the liver disease and tumour stage." (PMID 18577996, 2008). "Secreted frizzled-related protein 5 (SFRP5), an antagonist of the noncanonical WNT pathway, has a controversial role in liver disease." (PMID 34198988, 2021).
non-alcoholic steatohepatitis (5 papers, 2017 to 2023). "We found elevated SFRP5 expression in nonalcoholic steatohepatitis (NASH) in SAT and in mild simple steatosis (SS) and NASH in VAT." (PMID 36077270, 2022). "In vitro administration of Sfrp5 ameliorates hepatic lipid accumulation, inflammation and non-alcoholic steatohepatitis (NASH)." (PMID 34371968, 2021). "However, hepatic Sfrp5 protein levels were an independent predictor of NAFLD in a group of morbidly obese women, while, Sfrp5 mRNA and protein levels were lower in hepatocytes of non-alcoholic steatohepatitis (NASH) subjects compared to the control group." (PMID 34371968, 2021).
renal fibrosis (5 papers, 2017 to 2025). A final common manifestation of a wide variety of chronic kidney diseases characterized by glomerulosclerosis and tubulointerstitial fibrosis. "Recently, it was reported that SFRP5 protects against renal fibrosis by inhibiting the Wnt/β-catenin pathway." (PMID 40595027, 2025). "Taken together, these results indicate that SFRP5 inhibits the development of renal fibrosis by inactivating the Wnt/β-catenin signalling pathway." (PMID 40595027, 2025). "Thus, our study demonstrated that the aberrant expression of DNMT3B induced by high glucose and the resulting suppression of SFRP5 contribute to renal fibrosis, revealing a novel role of DNMT3B in the pathogenesis of DKD." (PMID 40595027, 2025). "Next, we examined the effect of SFRP5 on the Wnt/β-catenin signalling pathway in renal fibrosis." (PMID 40595027, 2025). "However, another study showed that the Sfrp5 gene is hypermethylated and downregulated in a mouse model of CKD, whereas injection of recombinant Sfrp5 inhibited Wnt signaling and attenuated renal fibrosis." (PMID 28851362, 2017).
colon carcinoma (4 papers, 2013 to 2024). "SFRP1, 2, 5 genes are frequently silenced by promoter hypermethylation in human CRC, a high percentage of DNA methylation in SFRP5 gene promoter has been detected by us in AOM-induced colon tumors (unpublished data)." (PMID 23717604, 2013). "SFRP5 harbors a bivalent promoter in normal colon tissue, with both H3K27me3 and H3K4me3 signals, and devoid of H3K27ac; in comparison, SFRP5 becomes DNA hypermethylated, inaccessible (undetectable ATAC-Seq signal) and strongly repressed in colon cancer." (PMID 33931649, 2021). "They reported that the inhibition of LSD1 in human colon carcinoma cells by biguanide and bisguanidine polyamine analogues resulted in a re-expression of aberrantly silenced genes, including SFRP1, SFRP4, SFRP5, and GATA5." (PMID 23922913, 2013). "A previous study reported that inhibition of LSD1 with polyamine analogs not only increased global levels of H3K4 methylation, but also H3K9ac, an epigenetic mark at active promoters, at the promoters of SFRP1, SFRP5, SFRP5 and GATA5 in human colon carcinoma cells." (PMID 38971831, 2024).
endothelial dysfunction (4 papers, 2017 to 2023). In vascular diseases, endothelial dysfunction is a systemic pathological state of the endothelium (the inner lining of blood vessels) and can be broadly defined as an imbalance between vasodilating and vasoconstricting substances produced by (or acting on) the endothelium. "This might be partially mediated by inhibition of pro-inflammatory effects of the Wnt5a/JNK signaling in macrophages which also plays an important role in adipose tissue inflammation and endothelial dysfunction and thus underlines the protective role of Sfrp5 on cardiovascular diseases." (PMID 28851362, 2017). "SFRP5 has also been shown to exhibit vascular protection, restoring Wnt5a-induced endothelial dysfunction and vascular relaxation in human vascular endothelial cells." (PMID 37504530, 2023).
hepatocellular carcinoma (4 papers, 2014 to 2021). A malignant tumor that arises from hepatocytes. "The levels of SFRP1, SFRP2, and SFRP5 methylation were also reported up-regulated in hepatocellular carcinoma tissues." (PMID 34205081, 2021). "The aim of this study was to investigate the characteristics of serum secreted frizzled-related protein 5 (SFRP5), an inhibitor of Wnt signaling, in hepatitis B virus (HBV)-associated infections and hepatocellular carcinoma (HCC) patients." (PMID 25120720, 2014).
liver fibrosis (4 papers, 2016 to 2026). "In contrast, SFRP5 deficiency exacerbated CCl4‐induced liver fibrosis by enhancing Wnt5a–JNK signaling." (PMID 41541657, 2026). "Inhibition of Wnt5a/Fz2 signaling by Sfrp5 and subsequent hepatic stellate cells inactivation, mitigated mouse liver fibrosis." (PMID 34371968, 2021). "During the progression of liver fibrosis in the Pten null model, Wnt ligands and signaling receptor are induced, concurrent with the reduction of sFRP5, a Wnt antagonist." (PMID 27307790, 2016). "SFRP5 appears to function similarly to SFRP1 in liver fibrosis." (PMID 41541657, 2026).
non-alcoholic fatty liver disease (4 papers, 2021 to 2024). "Clinical studies in adults suggest that Sfrp5 plays a prominent role in regulating adipogenesis, inflammation, glucose homeostasis, lipid metabolism, cardiovascular disease, non-alcoholic fatty-liver disease (NAFLD), and oxidative stress." (PMID 39339733, 2024).
steatosis (4 papers, 2016 to 2022). Increased lipid within the cytoplasm of cells. "Intraperitoneal injection of recombinant SFRP5 lowered the serum transaminases, reduced the intrahepatic steatosis and inflammation scores, and inhibited Kupffer cell activation and intrahepatic inflammatory adipokine expression in NASH model mice." (PMID 28824700, 2017). "Our study shows that this signal is likely relevant to the steatosis-induced fibrosis as several Wnt ligands and receptors are induced and sFRP5 is inhibited in the injured Pten null liver." (PMID 27307790, 2016). "Hence, we found significantly higher expression of SFRP5 in mild steatosis compared to absence (p = 0.001) or mod/sev degrees (p = 0.032); also, mod/sev group had an enhanced expression in comparison with the absence of steatosis cohort (p = 0.014)." (PMID 36077270, 2022). "In spite of the beneficial effect on steatosis, the efficacy of recombinant SFRP5 on intrahepatic inflammation is still unknown." (PMID 28824700, 2017). "Mice fed with MCDD developed elevated intrahepatic steatosis (2.20 ± 0.63) and inflammation scores (2.00 ± 0.47), which could be lowered by recombinant SFRP5 treatment (1.40 ± 0.97 and 1.40 ± 0.70, respectively, both P < 0.05)." (PMID 28824700, 2017). "Our research suggests that recombinant SFRP5 alleviates MCDD induced intrahepatic inflammation and steatosis." (PMID 28824700, 2017). "Our study verifies that recombinant SFRP5 can ameliorate MCDD induced intrahepatic inflammation and steatosis." (PMID 28824700, 2017). "Since we reported a peak of SFRP5 and WNT5A expressions in the SS mild stage in VAT samples, we decided to study the involvement of these genes focusing on the steatosis grades, regardless of inflammation or ballooning presence, in the analyzed cohort." (PMID 36077270, 2022).
cardiac hypertrophy (3 papers, 2021 to 2022). "In contrast, after intervention with the SFRP5 recombinant protein, the weight of the mouse hearts was decreased significantly, indicating that the SFRP5 recombinant protein can reverse ISO-induced cardiac hypertrophy." (PMID 35685732, 2022). "However, treatment with recombinant SFRP5 protein attenuated isoproterenol-induced cardiac hypertrophy." (PMID 35685732, 2022). "SFRP5 has been shown to be expressed in cardiomyocytes, and SFRP5 is upregulated in cardiomyocyte hypertrophy and plays a key role in reversing the progression of cardiac hypertrophy and cardiomyopathy through the AT1-R/Rho/ROCK 1/JNK signaling pathway." (PMID 35685732, 2022).